BDNF (brain derived neurotrophic factor)
Diseases named in the same sentence as BDNF in open-access papers (continued):
Sharing a sentence is not in itself a finding about the gene and the disease.
cancer (continued). "Signalling via the BDNF/TrkB pathway stimulates pro-survival signals, resistance to anoikis and altered cellular aggregation, all features of cancer cells and prerequisites of metastases formation." (PMID 21767406, 2011). "BDNF and TrkB are up-regulated in a variety of primary human tumors, including neuroblastoma, breast, bladder and ovarian cancers." (PMID 21999199, 2011). "Signaling via the BDNF/TrkB pathway stimulates pro-survival signals, resistance to anoikis and altered cellular aggregation, all features of cancer cells and prerequisites of metastases formation." (PMID 19173004, 2009). "In addition to NGF and GDNF, BDNF increases cancer cell invasion and chemotaxis toward nerves through TrkB‐mediated activation of phosphoinositide 3‐kinase (PI3K)/AKT and mitogen‐activated protein kinase (MAPK)/ERK signaling pathways." (PMID 41556039, 2026). "Numerous factors aside from cancer and cancer treatment can influence BDNF levels (i.e., age, gender, physical activity), thus having expected “normal” values for stratified patient populations may be necessary." (PMID 41403898, 2025). "Furthermore, the role of neurotrophic factors—particularly brain-derived neurotrophic factor—is explored, revealing their potential as molecular links between gut–brain axis modulation, cancer pathophysiology, and exercise-induced neuroprotection." (PMID 40969596, 2025). "Existing literature suggests that IL-6, NSP, pNF-H, and BDNF may serve as important biochemical markers of cognitive function in individuals with cancer." (PMID 41155494, 2025). "Thus, investigating the relationship between cytokines, BDNF, and cognitive outcomes in cancer survivors represents a promising area of research with potential implications for identifying individuals at risk and developing targeted interventions." (PMID 41155372, 2025). "This pilot study provides preliminary evidence that therapeutic yoga may positively influence neuroplasticity and metabolic regulation in cancer survivors, as indicated by increased plasma BDNF and ghrelin levels." (PMID 41128015, 2025). "The existing literature indicates that IL-6, NSP, pNF-H, and BDNF may serve as relevant biochemical markers of cognitive function in individuals with cancer." (PMID 41155494, 2025). "Other cancers may secrete EVs that contain brain-derived neurotrophic factor (BDNF) and nerve growth factor (NGF)." (PMID 40722712, 2025). "Here, we evaluate associations between plasma cytokines and BDNF and their relationship with cognition in a longitudinal study of adolescent and young adult cancer patients (AYAC) receiving chemotherapy and non-cancer controls (NC) (Clinicaltrials.gov: NCT03476070)." (PMID 40597835, 2025). "In vitro, recombinant BDNF promotes cancer cell migration and invasion." (PMID 41155494, 2025). "In addition, a recent clinical study in cancer survivors revealed that those with the Met/Met genotype of BDNF rs6265 reported significantly more severe cancer-related neuropathic pain and fatigue than those with other genotypes." (PMID 38254671, 2024). "Given the significance of BDNF in cancer treatment, research into its targets has begun to evolve." (PMID 39648800, 2024). "Additionally, evidence from animal studies also indicated that the synthesis and release of BDNF were significantly increased during inflammatory pain, cancer pain, and neuropathic pain." (PMID 38254671, 2024). "Our study suggests that female cancer survivors with the Met/Met genotype of BDNF rs6265 are likely to experience worse cancer-related fatigue and neuropathic pain and that cancer-related fatigue is a good predictor of co-occurring PN symptoms in this population." (PMID 37462904, 2024). "Overall, the results suggest that TNFR2 may be a key mediator in the development of both SCZ and cancer, possibly through the regulation of BDNF expression." (PMID 38592583, 2024). "However, despite maintaining normal distribution under cancer conditions, BDNF/TrkB expression are often upregulated." (PMID 39648800, 2024).
cancer (continued). "Moreover, both pain initiation and the maintenance of cancer pain were associated with an enlarged expression of nerve growth factor (NGF) and brain-derived neurotrophic factor (BDNF), and the increased release of tryptase and ATP." (PMID 38730655, 2024). "For example, BDNF plays a role in regulating the cell cycle, cell proliferation, and apoptosis and may potentially inhibit the self‐renewal of cancer cells." (PMID 39648800, 2024). "Our previous study found that male, non-depressed cancer patients with the Met carrier for BDNF rs6265 polymorphism experienced a protective advantage against cancer-related fatigue." (PMID 37462904, 2024). "For example, our results may have been affected by race, marital status, clinical stages of cancer, and radiation as the proportion of each item in the variables varied among the BDNF genotypes." (PMID 38379321, 2024). "On the other hand, brain-derived neurotrophic factor (BDNF) and neurotrophin-4/5 bind to TrkB and atypical activation of TrkB due to mutations or fusions involving NTRK2 can contribute to oncogenic transformation in certain cancers." (PMID 39124968, 2024). "We have previously found that male, non-depressed cancer patients with a BDNF Met allele reported less cancer-related fatigue than male cancer patients with the Val/Val genotype." (PMID 37462904, 2024). "They further suggested that BDNF could serve as a prognostic marker for early cancer detection and improve treatment outcomes." (PMID 39648800, 2024). "Our findings offer valuable insights for clinical practice that the symptom experience among female cancer survivors may vary based on BDNF genotypes." (PMID 37462904, 2024). "The targets of some of these genes are cancer-related genes, including BDNF, NTRK2, and MAPK3." (PMID 37100464, 2023). "Secondary outcome measures included differences between AYAC and HC on self‐perceived cognitive ability assessed by FACT‐Cog v3, health‐related quality of life, cancer‐related fatigue, and biomarkers (inflammatory cytokines and brain‐derived neurotrophic factor)." (PMID 36221816, 2023). "Potentially, cancer treatment has a major impact on the BDNF levels in carriers of the Met alleles which is not observed in those who did not receive cancer treatment." (PMID 37770565, 2023). "Several human studies have reported a positive correlation between BDNF levels and improved cognitive function in cancer patients, supporting our hypothesis that augmenting BDNF has great potential to mitigate CRCI." (PMID 36720792, 2023). "Brain-derived neurotrophic factor (BDNF) is overexpressed in many human cancers including PCa." (PMID 37091854, 2023). "We postulated that the effects of chronic chemotherapy on BDNF expression could persist long after the completion of chemotherapy and in cancer survivors, resulting in the long-term CRCI." (PMID 36720792, 2023). "We hypothesize that higher plasma BDNF levels are protective against cognitive toxicity among adolescent and young adult cancer patients (15–39 years old)." (PMID 37770565, 2023). "It was hypothesized on the basis of several studies that there must be an steady-state level of BDNF in plasma that ensures the prevention of initiation of cancer." (PMID 37460933, 2023). "Therefore, the BDNF/TrkB axis can be considered as a potential therapeutic target for several types of cancer." (PMID 37679418, 2023). "After adjusting for sociodemographic variables (age, gender, race, marital status, education years), cancer participants had lower BDNF levels (ng/mL) at baseline (median: 10.7 vs 21.6, p < 0.001) and 6-months post-baseline (median: 8.2 vs 15.3, p = 0.001) compared to non-cancer controls." (PMID 37770565, 2023). "Hence, the basis of this study stems from the breadth of our and others’ clinical data showing a positive correlation between the low BDNF levels with cognitive dysfunction in cancer patients receiving cytotoxic chemotherapy." (PMID 36720792, 2023).
cancer (continued). "Because both controls and anthracycline-receiving cancer patients were observed with statistically significant declines in BDNF levels, we conducted an exploratory analysis to assess how the observed changes in BDNF levels affect post-baseline cognitive outcomes among these participants." (PMID 37770565, 2023). "This study was conducted during the COVID-19 pandemic whereby reduced physical activity and higher distress levels could explain the observed change in plasma BDNF levels among non-cancer participants." (PMID 37770565, 2023). "The decreasing trend in plasma BDNF levels among non-cancer controls raises important questions as we had a priori hypothesized that levels should remain constant across time points in this group." (PMID 37770565, 2023). "In summary, our data provides pre-clinical evidence for a translationally feasible pharmacological approach, oral delivery of riluzole, to augment BDNF in vivo to mitigate cancer chemotherapy-induced adverse impact on neurogenesis, microglial activation, and cognitive function." (PMID 36720792, 2023). "Following this line of argument, targeting pathways leading to increased brain BDNF levels could potentially serve as a symptom management strategy for treating psychological symptoms among cancer patients." (PMID 35528795, 2022). "Upregulation of the BDNF/TRKB pathway in cancer cells promotes cell proliferation and survival via the RAS/MAPK, PI3K/PDK1/AKT, and PLCγ pathways, and induces anoikis suppression and epithelial-mesenchymal transition (EMT) via the induction of Zeb1, Twist, and/or Snail15–18." (PMID 36266462, 2022). "Next, with the aim of assessing more specifically the sensitivity of our approach, we study HEK293 living cells overexpressing tropomyosin-related kinase B (TrkB), a cancer-related membrane receptor, depending on the presence of its ligand, brain-derived neurotrophic factor (BDNF)." (PMID 36051442, 2022). "Secondary outcomes are Brain-derived neurotrophic factor (BDNF), brain function (functional MRI), Echocardiography, serum cortisol, Functional assessment of cancer therapy-cognition (FACT-Cog V3), perceived stress scale and Ryff Scales of Psychological Well-Being." (PMID 36185291, 2022). "Taken together, the results from our study and the available data from the literature offer a new research hypothesis in which both D-dimer and BDNF testing may improve the pre-test probability of acute PE in a specific subpopulation, such as cancer patients." (PMID 36078878, 2022). "Next, with the aim of assessing more precisely the sensitivity of our approach, we study HEK293 living cells overexpressing tropomyosin-related kinase B (TrkB), a cancer-related membrane receptor, depending on the presence of its ligand, brain-derived neurotrophic factor (BDNF)." (PMID 36051442, 2022). "Significant factors which might influence BDNF and TrkB levels are cancer biology and disease advancement." (PMID 34395067, 2021). "BDNF has since been shown to hold therapeutic significance for a range of cancers." (PMID 33574842, 2021). "In the early phase of carcinogenesis, BDNF might promote the growth of cancer by activating Th2 cells and therefore affect the survival of PAAD patients." (PMID 34777634, 2021). "This echanism may be responsible for the positive role that BDNF displays in cancers through immunoaugmentation." (PMID 34395067, 2021). "On the other hand, a decreased BDNF level induced by irradiation and the shift in the bacterial composition of gut microbiota may sensitize the cancer cells." (PMID 34572400, 2021). "Collectively, these findings supported the notion that BDNF might affect the survival time of cancer patients via interacting with Th2 cells." (PMID 34777634, 2021). "In addition, it is reported that BDNF-TrkB signaling can regulate cancer-endothelial cell interaction and affect the recurrence and metastasis of TNBC40,41." (PMID 34290315, 2021).
cancer (continued). "We also found that BDNF expression was correlated with high chemotherapeutics sensitivity and highly expressed immune checkpoints, making it a valuable biomarker in predicting the therapeutic benefits for chemotherapy and immunotherapy in cancer patients." (PMID 34777634, 2021). "In the previous study, it still remains unclear whether BDNF can be identified as oncogene or suppressor in different types of cancer." (PMID 34777634, 2021). "Moreover, several cancer-related pathways and the infiltration of immune cells, especially Th2 cells, were significantly correlated with BDNF mRNA levels." (PMID 34777634, 2021). "Next, we investigated the prognostic value of BDNF for cancer patients in different databases." (PMID 34777634, 2021). "Other authors also report the BDNF/TrkB pathway as a very promising target for cancer therapies." (PMID 34395067, 2021). "Here we aimed to determine the relationship between BDNF concentrations and cancer." (PMID 34395067, 2021). "A few studies have investigated serum BDNF concentrations in cancer." (PMID 34395067, 2021). "BDNF was shown to exert carcinogenic effects on different types of cancer and was reported to increase migration and survival of clear cell renal cell carcinoma, induce cell metastasis in human colon cancer, and promote proliferation and invasion of lung squamous cell carcinoma." (PMID 34209215, 2021). "In co-culture, the addition of BDNF did not affect migration of Schwann or cancer cells but enhanced the intercalation of cell types and increased Schwann cell-associated cancer cell dispersion." (PMID 34885121, 2021). "However, the biological function and mechanism of action of BDNF in cancer progression are still unclear." (PMID 34771682, 2021). "For this reason, we compared the TrkB and BDNF levels in spheroid versus adherent cancer cells." (PMID 33294440, 2020). "Contrarily to primary cancer cells, in brain metastasis, we have documented an increasing expression of BDNF, which may be responsible for favoring cancer engraftment and metastatic progression." (PMID 33294440, 2020). "BDNF can induce cancer cell survival, proliferation, resistance to anoikis and angiogenesis." (PMID 32183322, 2020). "BDNF may be extremely important for the survival of metastatic cancer cells within the central nervous system." (PMID 33294440, 2020). "Four growth factors (NGF, BDNF, NT-3, and NT-4/5) and 2 types of receptors (Trk tyrosine kinase receptors and P75NTR) constitute the neurotrophin signaling pathway, which is associated with cancer stem cells." (PMID 33224315, 2020). "This time point may not be the optimal one to measure BDNF dynamics in 40% O2 group but increased Vimentin and decreased E-Cadherin expression in cancer cell were already present to demonstrate a pick of undetected BDNF expression." (PMID 32183322, 2020). "Moreover, BDNF was recently shown to be involved in cancer progression and to be modulated by chronic stress and activation of the SNS71." (PMID 32587352, 2020). "While these studies cannot define the exact contribution of astrocytic vs cancer-cell BDNF to E2-induced BMs, targeting BDNF/TrkB function in vivo significantly blocked BM, providing compelling evidence that this BDNF/TrkB signaling is critical for E2-induced brain colonization." (PMID 30796353, 2019). "BDNF and its receptor tropomyosin receptor kinase B (TrkB) are usually upregulated in diverse cancer types, and stimulate a series of downstream pathways resulting increasing cancer cell growth, proliferation, survival, migration and EMT." (PMID 35582568, 2019). "NGF/TRKA and BDNF/TRKB are the main NTs studied in the context of cancer." (PMID 31608227, 2019).
cancer (continued). "This discrepancy may be explained by animal studies where the expression and release of BDNF have been shown to be heavily dependent on other physiological elements, such as stress and inflammation, which are elevated in cancer patients undergoing treatment." (PMID 30382534, 2019). "In addition, the chromosomal locus containing miR-204 is frequently lost in cancers, resulting in its lower expression and resulted in BDNF/TrkB overexpression and activation of the AKT/mTOR/Rac1 signaling pathway." (PMID 31480771, 2019). "The role of HGF/c-Met and BDNF/TrkB signaling is reported in several cancers including HCC." (PMID 30885237, 2019). "Surprisingly, E2 increased BDNF in astrocytes and by a paracrine mechanism, in cancer cells." (PMID 30796353, 2019). "What we could suggest from cancer cell migration studies is that in the presence of the BDNF, p75NTR may be activated by TrkB and Kidins220 upon ephrin receptor phosphorylation leading to STAT3 activation and RhoA inhibition." (PMID 30190671, 2018). "In conclusion, our findings reveal a potent protective role of BDNF against Dox‐induced cardiotoxicity by activating Akt signalling, which may facilitate the safe use of Dox in cancer treatment." (PMID 28098423, 2017). "Therefore, this study aimed to investigate determine the therapeutic role of BDNF against Dox‐induced cardiotoxicity by regulating Akt or MAPK signals to facilitate their safe use in cancer treatment." (PMID 28098423, 2017). "BDNF immunostaining was observed in the cytoplasm of cancer cells." (PMID 26926340, 2016). "However, despite the considerable amount of studies on BDNF have been reported in human cancer, here we investigated the function of BDNF in lung SCC and ADC." (PMID 26926340, 2016). "The further electrophysiological recording studies revealed that intrathecal delivery of TrkB-Fc chimera (1.5 μg, day 3 to day 15), which quenching the endogenous BDNF, significantly ameliorated the increase of glutamatergic strength in the dorsal horn neurons of the rats with cancer-induced pain." (PMID 24886294, 2014). "BDNF has been shown to promote anti-apoptotic proteins of lung AC and several other cancer cells." (PMID 23451142, 2013). "After the discovery of the involvement of the BDNF/TrkB cascade in cancer biology, it is appreciated that the inhibition of TrkB activity might be beneficial in a clinical oncology setting." (PMID 23936232, 2013). "BDNF has been reported to be expressed by many types of human cancer cells." (PMID 23874483, 2013). "Previous studies have shown that BDNF increases cell migration and invasion in human cancer cells." (PMID 23874483, 2013). "It has been reported that BDNF stimulates directional migration and invasion of human cancer cells." (PMID 23874483, 2013). "Given that exercise increases BDNF activity and causes angiogenesis, and in considering evidence that BDNF serves as an angiogenic factor in some cancers, it is reasonable to hypothesize that BDNF may also be involved in exercise-induced angiogenesis." (PMID 24961267, 2012). "We hypothesized that if the cancer-derived TRKB mutations confer a gain of function, they may transform epithelial cells even in the absence (or with reduced levels) of BDNF." (PMID 21379385, 2011). "However, similar to cytokines, findings for BDNF are variable across studies, likely due to small sample sizes, heterogeneous cancer types, differences in treatment regimens, timing of sample collection, and individual variability in systemic and CNS responses." (PMID 41572047, 2026). "However, there is growing research on the role of BDNF in opioid use for cancer and pain." (PMID 40973140, 2025). "Notably, some studies in cancer patients have also reported elevated BDNF levels." (PMID 41155372, 2025).